ARHGAP11B-DT (ARHGAP11B divergent transcript)
Gene: Long non-coding RNA gene on chromosome 15 (30,481,013 to 30,626,012, reverse strand). Ensembl gene ENSG00000247728.
Gene Ontology:
Biological process: RNA processing
Cellular component: nucleolus